PIK3CA (phosphatidylinositol-4,5-bisphosphate 3-kinase catalytic subunit alpha)
Diseases named in the same sentence as PIK3CA in open-access papers (continued):
Sharing a sentence is not in itself a finding about the gene and the disease.
cervical carcinoma (continued). "The PI3K-specific inhibitors Alpelisib (BYL-719) and Inavolisib (GDC0077) inhibit the proliferation of multiple PIK3CA-mutated cervical cancer cell lines, but not a PIK3CA wild-type (WT) line." (PMID 41646800, 2026). "There are limited and conflicting reports on the prognostic utility of PIK3CA and the assessment of PIK3CA in cervical cancer before radical hysterectomy may help identify patients at higher risk of node-positive disease." (PMID 40270962, 2025). "As such, it has been well documented that PIK3CA is overexpressed in cervical cancer." (PMID 39590348, 2024). "Interestingly, PIK3CA is also significantly mutated in other HPV-associated cancers, such as head and neck or cervical cancers." (PMID 36357817, 2023). "This study indicated that PIK3CA mutational status with CNV status (delete, gain, or normal) might be important in predicting outcome in cervical cancer patients." (PMID 35242279, 2022). "PIK3CA is the most commonly mutated gene in human papillomavirus (HPV) associated squamous cell carcinoma and is an important factor in predicting the prognosis of cervical cancer patients." (PMID 35935970, 2022). "Indeed, the PIK3CA gene is described as the top altered gene in cervical carcinoma along with the MTOR, KMT2D and FAT1 genes." (PMID 36010253, 2022). "For example, PIK3CA CNV gain was noted in cervical cancer patients." (PMID 35242279, 2022). "We did not investigate the association of PIK3CA mutations and survival outcomes of cervical cancer patients in our cohort." (PMID 35205332, 2022). "Furthermore, using bioinformatics analysis in cervical cancer and head and neck cancer patients with PIK3CA alterations, FSCN1-co-expressed genes were enriched in the apoptosis pathway." (PMID 34249689, 2021). "Amplification of PIK3CA is observed in 15.8% of samples in the cervical carcinoma cohort of TCGA." (PMID 34436017, 2021). "In addition, we found that FSCN1 gene expression was lower in patients with cervical cancer (P < 0.001) and head and neck tumors (P < 0.001) with PIK3CA alterations than in those in the wild-type group." (PMID 34249689, 2021). "FSCN1 may be a synthetic lethality gene with PIK3CA and its expression level may serve as a biomarker for prognosis and radiotherapy response in cervical cancer and head and neck cancer." (PMID 34249689, 2021). "PIK3CA mutations are one of the most frequently detected mutations in cervical cancer regardless of ethnicity." (PMID 34584128, 2021). "Patients with cervical squamous carcinomas and PIK3CA mutations tend to present in a more advanced age than the cervical cancer patients without PIK3CA mutations." (PMID 33435133, 2021). "In addition, ACTL6A co-expressed several important genes in the cervical cancer 3q amplicon, including PIK3CA, SOX2 and TP63." (PMID 34395295, 2021). "However, only limited evidences supported the correlation of PIK3CA alterations with the response to the mTOR inhibitors in cervical carcinoma." (PMID 35071000, 2021). "The subset of cervical cancers with PIK3CA mutations tend to have additional mutations in cancer-associated genes of oncogenic pathways more frequently than patients without PIK3CA mutations." (PMID 33435133, 2021). "The prevalence of mutations of the backbone component genes of the pathway is higher in cervical cancers with PIK3CA mutations compared with the group without PIK3CA mutations." (PMID 33435133, 2021). "Interestingly, we found 11 genes that were correlated with FSCN1 only in the PIK3CA-altered group in both cervical cancer and head and neck cancer." (PMID 34249689, 2021). "PIK3CA has been found to play a role in gynecological tumors such as cervical cancer." (PMID 32489319, 2020).
cervical carcinoma (continued). "As has been previously noted, the PIK3CA c.1633G>A (p.E545K) mutation occurs at one such APOBEC motif and this association may account for the frequency of this mutation across cervix cancer subtypes." (PMID 32544169, 2020). "A recent study in cervical cancer showed that PIK3CA mutation status did not have any significant association with clinicopathological characteristics but highlighted an association with poor overall survival." (PMID 31905960, 2019). "PIK3CA and MDM2 SNP309 have been studied to be associated with cervical cancer." (PMID 31350972, 2019). "Comparison of the different histological types of cervical cancer may also be warranted for future studies to determine whether the frequency of PIK3CA mutation and MDM2 polymorphism differ based on the histological types of cervical cancer." (PMID 31350972, 2019). "PIK3CA gene mutation was present among Filipino cervical cancer patients and not in control patients." (PMID 31350972, 2019). "Thus, we determined the prevalence of PIK3CA and MDM2 mutations in Filipino cervical cancer patients." (PMID 31350972, 2019). "Among the eight nonresponder patients with cervical cancer, four received everolimus on the basis of PIK3CA mutation (Glu545Lys), two on the basis of PTEN inactivation, and two on the basis of AKT1 mutation (Glu17Lys)." (PMID 32914004, 2018). "To date, the role of autophagy as a potential adaptive mechanism of resistance to PI3K inhibitors has not been investigated in cervical cancer with PIK3CA mutations." (PMID 28036259, 2017). "Interestingly, mutations in the most frequently activated gene, PIK3CA, are more common in HPV16-positive than in HPV18- and HPV45-positive cervical cancers." (PMID 27784002, 2017). "One recent study of 228 cervical cancers using TCGA data identified SHKBP1, ERBB3, CASP8, HLA-A, and TGFBR2 as novel significantly mutated genes, and previously identified pathogenic genes including PIK3CA, EP300, ARID1A, and NFE2L2 were also confirmed." (PMID 28390392, 2017). "Furthermore, EP300, ARID1A, FBXW7, NFE2L2, PIK3CA, and ERBB2 have all been previously reported as pathogenic genes in cervical cancer, and we highlighted the roles of MLL2, MLL3, and CREBBP in the tumorigenesis." (PMID 28390392, 2017). "To investigate the role of autophagy in the response to PI3K inhibitors, we assessed autophagy induction in cervical cancer cell lines with or without PIK3CA mutations." (PMID 28036259, 2017). "HPV-driven cancers of the cervix, head and neck, and penis share copy number alteration sites, most notably copy number gains in 3q, which in addition to PIK3CA contains the telomerase RNA component (TERC), MDS1 and EVI1 complex locus (MECOM), SRY-box 2 (SOX2), and TP63 genes." (PMID 28771191, 2017). "Together, these results reveal that expression of PIK3CA-E545K in cervical cancer cell lines promotes both cisplatin resistance and a cell migratory phenotype and that both cisplatin resistance and cell migration can be mitigated at least in part, by inhibition of the PI3K pathway using GDC-0941." (PMID 27489350, 2016).
cervical carcinoma (continued). "The chemoresistant effect of RAS or PIK3CA pathway activation has been described in non-small cell lung cancer and colorectal preclinical models and clinically in patients with cervical cancer; therefore, this may be a true effect." (PMID 27298411, 2016). "Specifically, CaSki cells showed ~30% survival at 2 μM cisplatin, compared to ~3% and ~1% in SiHa and HeLa respectively, suggesting that expression of PIK3CA-E545K may confer resistance to cisplatin in cervical cancer cells." (PMID 27489350, 2016). "Therefore, the identification and characterization of cervical cancer patients harboring mutant PIK3CA are important for designing clinical trials investigating PI3K pathway inhibitors." (PMID 26358014, 2015). "Cervical carcinomas showed significant overexpression of PIK3CA compared to controls." (PMID 21663621, 2011). "PIK3CA was specifically found to be amplified and overexpressed in ovarian and cervical cancer." (PMID 16168105, 2005). "PIK3CA, the gene encoding the 110-kDa subunit of PI3K, was mapped to 3q26, an area amplified in various human cancers including ovarian, head and neck, breast, urinary tract, and cervical cancers." (PMID 16168105, 2005). "Importantly, these alterations have therapeutic relevance: several PI3K/AKT/mTOR inhibitors have been investigated in early phase trials for gynecologic tumors, and the PI3Kα inhibitor alpelisib has shown preclinical efficacy against PIK3CA-mutant cervical carcinoma models." (PMID 41597409, 2026). "Interestingly, another study from a Ugandan cervical cancer cohort reported that mutation and expression of the PIK3CA gene was markedly lower in WLWH compared to women without HIV." (PMID 40661570, 2025). "Additionally, we observed the expression of miR-29a and PIK3CA in the biopsy specimens from cervical cancer patients and non-cervical cancer patients, finding that the miR-29a levels were lower and the PIK3CA levels were higher in cervical cancer patients compared to normal individuals." (PMID 39590348, 2024). "Indeed, PIK3CA is usually either mutated or amplified in several human cancers, including colorectal cancer (CRC), breast, lung, gastric, prostate, and cervical cancer." (PMID 37596643, 2023). "Additionally, both HLA-A and HLA-B interacted with PIK3CA, which were reported to confer radioresistance to cervical cancer, suggesting that HLA-A and HLA-B may also be involved in radiotherapeutic resistance of cervical cancer." (PMID 35205332, 2022). "In addition, PIK3CA mutated cervical cancers display a higher tumor mutation burden (TMB) than non-mutated cancers." (PMID 33435133, 2021). "PIK3CA (phosphatidylinositol-4,5-bisphosphat-3-kinase, catalytic subunit alpha), PTEN and MPK1 (mitogen-activated protein kinase 1) were confirmed as significantly mutated genes (SMG), while ERBB3, CASP8, HLA-A and TGFBR were identified as novel SMGs in cervical cancer." (PMID 34830902, 2021). "These discordant findings are consistent with a systemic review by Pergialiotis and colleagues that included twelve research articles and a total of 2196 cervical cancer patients and demonstrated no impact of PIK3CA mutations on treatment response and survival." (PMID 34830902, 2021). "This suggests that PIK3CA activation is involved in paclitaxel resistance and may thus be a clinically relevant target to overcome chemoresistance and prevent metastasis during paclitaxel chemotherapy in cervical cancer." (PMID 31295843, 2019). "However, the role of mutant PIK3CA on metabolism in cervical cancer is less researched." (PMID 30547809, 2018). "Consequently, we inferred that SIRT3 might be involved in glucose metabolism in cervical cancer cells with mutant PIK3CA, which was adversely regulated by β-catenin." (PMID 30547809, 2018).
cervical carcinoma (continued). "Additionally, 14-3-3ζ knockdown alone significantly reduced the viability of C33A cells, suggesting that 14-3-3ζ might also be a potential therapeutic target in PIK3CA-mutant cervical cancer." (PMID 28036259, 2017). "However, the clinicopathological characteristics and prognostic impact of PIK3CA-mutated cervical cancer have not been well established." (PMID 26358014, 2015). "Additionally, low levels PIK3CA amplifications were found in 40%-74% of cervical carcinomas." (PMID 21663621, 2011). "PIK3CA, the largest catalytic subunit of PI3K, is the second most altered gene in cervical cancer participants listed in cBioPortal and has emerged as the topmost mutated gene in cervical cancer participants across ethnicities." (PMID 40661570, 2025). "Dysregulation of the PI3K/Akt/mTOR axis—frequently due to genetic alterations in components such as PIK3CA, PTEN, Akt and mTOR—is a common event in cervical cancer and contributes to tumour progression, metastasis and resistance to apoptosis." (PMID 41261348, 2025). "First, we examined the expression of PIK3CA, a gene related to the PIK3/AKT/mTOR signaling pathway, across various cervical cancer cell lines." (PMID 39590348, 2024). "Mutations or alterations in the expression of human oncogenes, including MYC, PIK3CA and RAS, have been reported in cervical cancer." (PMID 36763589, 2023). "Complementing our findings, previous studies have reported perturbations in PIK3CA, an oncogene part of the ERBB2/PI3K/AKT/mTOR pathway with a battery of druggable targets, present in over 50% of cervical tumor and cervical cancer cell lines." (PMID 36201462, 2022). "For example, mutant PIK3CA (E542K and E545K) can enhance glucose metabolism and cell proliferation in vitro and in vivo via the β-catenin/SIRT3 signaling axis in cervical cancer cells." (PMID 34249689, 2021). "A high prevalence of genes, namely, PIK3CA, EP300, FBXW7, and PTEN was identified as the genomic feature of Western cervical cancer patients, and inferred as novel potential therapeutic targets for drug development in future." (PMID 35071000, 2021). "The mutation data sheet downloaded from the CCLE website was first summarized and western blots were performed to assess the difference in expression of PIK3CA in four human papilloma virus (HPV)-positive types, including five cervical cancer cell lines." (PMID 31295843, 2019). "In this study, we determine the frequency of PIK3CA and MDM2 SNP309 (rs2279744) in Filipino cervical cancer patients." (PMID 31350972, 2019). "Another study in 15 cervical cancer patients from Hong Kong revealed frequently altered genes, including FAT1, ARID1A, ERBB2, and PIK3CA." (PMID 28390392, 2017). "A landmark multi-omic analysis by The Cancer Genome Atlas (TCGA) provided a comprehensive molecular characterization of cervical cancer, identifying APOBEC-driven mutagenesis as a dominant process and recurrent alterations in PIK3CA, PTEN, KRAS, ERBB3, CASP8, HLA-A, SHKBP1, and TGFBR2." (PMID 41590369, 2026). "Our results show that a few alterations of host oncogenes, such as MYC, PIK3CA, MEK1 and KRAS, in conjunction with the episomal form of HPV16, might be sufficient to drive development of cervical cancer." (PMID 36763589, 2023).
cervical carcinoma (continued). "DNA from 46 cervical cancer tissue samples were extracted and amplified by PCR, using 1 set of primers designed for EGFR and 2 sets of primers designed for two different regions of both PIK3CA and KRAS gene." (PMID 33736612, 2021). "We uncovered that genetic alterations in PIK3CA, PTEN, ERBB3, and PI3K/AKT pathway, as well as TMB, could be novel predictive biomarkers in patients with cervical cancer treated with PD-1 inhibitor combination therapy." (PMID 34011535, 2021). "In summary, we uncovered that genetic alterations in PIK3CA, PTEN, ERBB3, and PI3K/AKT pathway could be novel predictive biomarkers in patients with cervical cancer treated with PD-1 inhibitor combination therapy." (PMID 34011535, 2021). "At this stage, there is still no clear association between the presence of PIK3CA mutation and MDM2 polymorphisms and the occurrence of cervical cancer." (PMID 31350972, 2019). "In contrast, mutation and/or amplification of PIK3CA are a common feature of both HPV-positive and -negative HNSCCs and cervical cancers." (PMID 27784002, 2017). "Functional studies in cervical cells are restricted to the common hrHPV positive cervical cancer cell lines such as SiHa, HeLa and CaSki and did not include the explicit analysis of PIK3CA as a candidate oncogene." (PMID 21663621, 2011). "Indeed, we found that significant co-occurrence of MYC amplification and PIK3CA alteration in TCGA of cervical cancer though the status of HPV genomes is not known." (PMID 36763589, 2023). "Moreover, the role of PIK3CA in cervical cancer was further highlighted by comparing with the ONCOKB database, especially for E545K and E542K, which were reported to confer radioresistance to cervical cancer." (PMID 35205332, 2022). "PIK3CA and PTEN genomic mutations may be more accurate biomarkers for cervical cancer outcome only for patients who are non-obese." (PMID 29423104, 2018).